PTGER1 (prostaglandin E receptor 1)
Diseases named in the same sentence as PTGER1 in open-access papers (continued):
Sharing a sentence is not in itself a finding about the gene and the disease.
cancer (21 papers, 2006 to 2025). A tumor composed of atypical neoplastic, often pleomorphic cells that invade other tissues. "We performed a pan-cancer, multi-omics analysis of PTGER1 to evaluate its diagnostic, prognostic, and immunological relevance across human cancers." (PMID 41583321, 2025). "In this context, the prostaglandin E receptor 1 (PTGER1) has emerged as a significant mediator of inflammation and cancer progression, yet its value as a diagnostic or prognostic biomarker has not been systematically investigated in the literature." (PMID 41583321, 2025). "This analysis integrates data from large-scale cancer genomics studies to uncover associations between PTGER1 aberrations and oncogenic processes." (PMID 41583321, 2025). "Across 32 cancer studies in the TCGA pan-cancer dataset, analysis of 10,967 samples from 10,953 patients revealed that PTGER1 harbours mutations in approximately 3% of cases." (PMID 41583321, 2025). "PTGER1 was analyzed using cBioPortal, an open-access, web-based platform that enables exploration of gene alterations across multiple cancer types to investigate its mutational landscape, expression patterns, and potential clinical relevance." (PMID 41583321, 2025). "Cross-referencing across two or more databases showed that high PTGER1 expression was consistently linked to poor prognosis in several cancers." (PMID 41583321, 2025). "The downregulation of PTGER1 in malignancies raises questions about the interplay between prostaglandin signalling and cancer progression." (PMID 41583321, 2025). "We assessed PTGER1 expression across two cancers: KIRC and LIHC, under a strict threshold of ILog2FCI>=2 and adjusted P-value < 0.05." (PMID 41583321, 2025). "From a genomic perspective, across a variety of cancers, PTGER1 was altered in approximately <2% (160 samples out of 10960 samples) primarily through gene amplification." (PMID 41583321, 2025). "The relationship between PTGER1 expression and the immune microenvironment was evaluated across multiple human cancer types." (PMID 41583321, 2025). "Analysis via UALCAN, applied as a final validation layer, highlighted cancer-specific modulation of PTGER1 expression across nine TIMER-identified malignancies." (PMID 41583321, 2025). "Analysis of methylation in the promoter region of PTGER1 across multiple cancer types revealed distinct epigenetic regulation profiles." (PMID 41583321, 2025). "Overall, these results position PTGER1 as a candidate stratification tool requiring cancer-selective application and expanded clinical validation." (PMID 41583321, 2025). "Survival analysis identified PTGER1 as a clinically relevant prognostic indicator with cancer type specificity." (PMID 41583321, 2025). "PTGER1 expression was further interrogated using the UALCAN database, focusing on cancer types that exhibited concordant expression patterns across at least two independent platforms utilizing GEPIA, UALCAN, and TIMER." (PMID 41583321, 2025). "CYSLTR1 and PTGER4 are primarily expressed by immune cells in human cancers, while LTB4R, PTGER1 and PTGER3 are found in neuroendocrine and tuft cells." (PMID 37386128, 2023). "PTGDR, PTGDR2, PTGER1, PTGER3, and PTGFR genes have the median expression value of about 1 FPKM (Fragments Per Kilobase Million), while other genes are expressed in the range of 1–5 FPKM, regardless of cancer specificity." (PMID 35453789, 2022).
infection (5 papers, 2015 to 2022). The state of being infected such as from the introduction of a foreign agent such as serum, vaccine, antigenic substance or organism. "Since the effector function of PGE2 produced by myeloid cells depends on its binding to EP receptors, we studied gene expression of its 4 receptors, EP-1 (Ptger1), EP-2 (Ptger2), EP-3 (Ptger3) and EP-4 (Ptger4), in hearts of mice during infection." (PMID 26305786, 2015).
PTGER1 also shares sentences with these, for which no sentence is quoted: breast cancer (16 papers); diabetic nephropathy (6); colorectal cancer (4); epithelial ovarian cancer (4); ischemic stroke (4); melanoma (4); Arthritis (3); asthma (3); glioma (3); ischemia (3); kidney disease (3); neuroblastoma (3); ovarian cancer (3); renal fibrosis (3); skin tumor (3); adenocarcinoma (2); Allergy (2); cerebral artery (2); Cerebral ischemia (2); cervical cancer (2); colitis (2); glioblastoma (2); hemorrhagic stroke (2); intestinal polyp (2); non-small cell lung carcinoma (2); oral cancer (2); polyp (2); rheumatoid arthritis (2); type 1 diabetes (2); vulvar carcinoma (2).
A further 60 diseases each share a sentence with PTGER1 in 1 paper.